INPP5B (inositol polyphosphate-5-phosphatase B)
Description:
Regulates phosphatidylinositol 4,5-bisphosphate (PtdIns(4,5)P2) cellular levels by cleaving the phosphate at the 5-position producing PtdIns(4)P. Also hydrolyzes the 5-position phosphate from inositol 1,4,5-trisphosphate (Ins(1,4,5)P3), thereby modulating cellular signaling events.
Synonyms: 5PTase
Tractability: Small molecule: a structure with a bound ligand is known. Antibody: UniProt places it where antibodies can reach, with high confidence; its Gene Ontology location is reachable by antibodies, with high confidence. PROTAC: ubiquitination databases record sites on it; its protein half-life has been measured; a small molecule that binds it is known.
Target class: Enzyme; Phosphatase
Gene: Protein-coding gene on chromosome 1 (37,860,696 to 37,947,077, reverse strand). Ensembl gene ENSG00000204084.
Subcellular location: Cytoplasm, cytosol; Endoplasmic reticulum-Golgi intermediate compartment; Early endosome membrane; Membrane; Cytoplasmic vesicle, phagosome membrane; Golgi apparatus
Subcellular location (Human Protein Atlas): Cytosol; Primary cilium tip
Pathways (Reactome):
Metabolism: Synthesis of IP2, IP, and Ins in the cytosol; Synthesis of IP3 and IP4 in the cytosol
Gene Ontology:
Molecular function: inositol-1,4,5-trisphosphate 5-phosphatase activity; phosphatidylinositol-4,5-bisphosphate 5-phosphatase activity; protein binding; inositol-1,3,4,5-tetrakisphosphate 5-phosphatase activity; inositol phosphate phosphatase activity; inositol-polyphosphate 5-phosphatase activity; phosphatase activity
Biological process: phosphatidylinositol dephosphorylation; inositol phosphate metabolic process; signal transduction
Cellular component: cytosol; early endosome membrane; endoplasmic reticulum-Golgi intermediate compartment; Golgi apparatus; membrane; cytoplasm; neuron projection; plasma membrane; phagocytic vesicle membrane
Genetic constraint (gnomAD): Loss-of-function variants: 62 observed, 79.86 expected, observed/expected ratio (o/e) 0.78, 90% interval 0.63 to 0.96. The upper end of that interval is the gene's LOEUF score, 0.96, which puts it in group 4 of 6, group 1 being the genes least tolerant of losing a copy. Missense variants: 831 observed, 969.39 expected, observed/expected ratio (o/e) 0.86, 90% interval 0.81 to 0.91. Synonymous variants: 335 observed, 368.36 expected, observed/expected ratio (o/e) 0.91, 90% interval 0.83 to 1.
Homologues: Orthologues: macaque INPP5B (96% identical), chimpanzee INPP5B (95% identical), dog INPP5B (90% identical), rabbit INPP5B (89% identical), guinea pig INPP5B (88% identical), pig INPP5B (88% identical), rat Inpp5b (87% identical), mouse Inpp5b (86% identical), tropical clawed frog inpp5b (60% identical), zebrafish inpp5b (59% identical), Drosophila melanogaster Ocrl (30% identical), Caenorhabditis elegans ocrl-1 (24% identical). Paralogues in human: OCRL (45% identical), SYNJ1 (24% identical), SYNJ2 (23% identical), INPP5J (21% identical), INPPL1 (19% identical), INPP5D (19% identical), INPP5E (15% identical), INPP5F (14% identical), INPP5K (14% identical), FIG4 (13% identical), SACM1L (10% identical), SH2D1A (4% identical), and 1 more.
Diseases named in the same sentence as INPP5B in open-access papers:
INPP5B is named in the same sentence as 31 diseases in open-access papers, as found by Europe PMC text mining. Sharing a sentence is not in itself a finding about the gene and the disease. The quoted sentences say what the papers report.
Lowe syndrome (14 papers, 2013 to 2023). "Current studies on INPP5b have focused on its role in Lowe Syndrome and Type 2 DENT disease, while its role in lung cancer has not been reported." (PMID 34430085, 2021). "Evidence of differential expression of OCRL and INPP5B in human and mice is also presented that potentially explains the mild phenotype of Lowe syndrome murine models." (PMID 23805271, 2013). "Furthermore, expressing humanised INPP5B in Ocrl/Inpp5b knockout mice shows proximal tubule dysfunction (low molecular weight proteinuria, aminoaciduria) similar to Lowe syndrome and Dent II disease." (PMID 34069732, 2021). "However, another mouse model with deletion of both Ocrl1 and another type II PtdIns4,5P2 5-phosphatase Inpp5b, but overexpression of human INPP5B display disorders related to Lowe syndrome." (PMID 32244264, 2020). "Reconstitution of Ocrl;Inpp5b double KO mice with human INPP5B rescued lethality but still resulted in a Lowe syndrome-like phenotype including aminoaciduria, proteinuria and growth retardation, indicating lack of full functional conservation between mouse and human INPP5B." (PMID 32970140, 2020). "Future therapeutic targets to upregulate INPP5B in the trabecular meshwork and the lens epithelium may help ameliorate or even reverse the clinical development of ocular phenotypes in Lowe syndrome." (PMID 23805271, 2013). "Overlapping functions for some of the 5′phosphatases have been reported for example OCRL1−/− mice do not develop Lowe’s disease since loss of OCRL1 was compensated by a highly homologous protein Inpp5b." (PMID 24069021, 2013). "Specifically, we selected synaptojanin 1⁄2 (SYNJ1/2), INPP5E, INPP5J, oculocerebrorenal syndrome of Lowe (OCRL), INPP5B, and INPP5K, of which INPP5E/B and OCRL have already been shown to alter ciliary lipid composition." (PMID 38110903, 2023). "OCRL (Inositol Polyphosphate-5-Phosphatase) KO mice did not exhibit Lowe syndrome/Dent disease unless Inpp5b (Inositol Polyphosphate-5-Phosphatase B) was deleted in the proximal tubule as well." (PMID 32150856, 2020). "Collectively, these data illustrate the possibility that OCRL-related disorders could be rescued by increasing levels of INPP5B, perhaps via AAV gene delivery or via drugs known to upregulate INPP5B expression in Lowe syndrome-affected tissues." (PMID 31413155, 2019). "Although Ocrl knockout mice do not display the typical symptoms of Lowe syndrome, Inpp5b knockout mice exhibit male sterility, which has limited functional studies to distinguish their roles in Lowes syndrome." (PMID 23805271, 2013). "Although absent from trabecular meshwork and lens epithelium, INPP5B in the retina may explain the lack of retinitis pigmentosa (RP) phenotype in Lowe syndrome." (PMID 23805271, 2013).
Dent 2 disease (3 papers, 2016 to 2021). "A patient with Dent 2 disease was found to have mutations in both CLCN5 and OCRL genes, and an intermediary phenotype between DD and LS, while another case with OCRL and INPP5B variants presented with a Chiari I malformation." (PMID 32150856, 2020).
lung adenocarcinoma (3 papers, 2021 to 2024). A carcinoma that arises from the lung and is characterized by the presence of malignant glandular epithelial cells. "This study aims to investigate the potential role of INPP5B as a diagnostic and prognostic biomarker for lung adenocarcinoma (LUAD), as well as its biological functions and molecular mechanisms in LUAD." (PMID 35568951, 2022). "Here, we demonstrated a causal relationship between decreased INPP5B expression and the development of lung adenocarcinoma (LUAD) by using combinatorial tools consisting of both bioinformatics analysis and experimental studies." (PMID 35568951, 2022). "The decreased expression of INPP5B is associated with poor prognosis in lung adenocarcinoma." (PMID 38741142, 2024). "In addition, INPP5B is also significantly down-regulated in lung adenocarcinoma." (PMID 34430085, 2021). "A novel four-gene signature (INPP5B, FOSL2, CDCA3, RASAL2) was established to predict relapse-related survival outcomes in patients with early lung adenocarcinoma after surgery." (PMID 34430085, 2021).
Anophthalmia (1 paper, 2013). Absence of the globe or eyeball. "It is possible that the loss of both OCRL and INPP5B in humans may result in anophthalmia as in the zebrafish model." (PMID 23805271, 2013). "In fact, the loss of Inpp5b results in a more severe phenotype of anophthalmia, which is not present in the ocrl-MO injected fish, and suggests inpp5b is required in cilia development in the zebrafish." (PMID 23805271, 2013).
asthma (1 paper, 2023). "The INPP5B gene encodes an inositol polyphosphate-5-phosphatase B protein that regulates calcium signaling, which is involved in inflammatory cellular responses and interactive signaling pathways that mediate the development of asthma." (PMID 37875944, 2023).
B cell lymphoma (1 paper, 2022). "To determine whether the role of INPP5B in the B cell response to BCR stimulation is conserved between species, we analyzed two human B cell types: the well-studied Ramos B cell lymphoma model and primary B cells isolated from healthy donors." (PMID 35878408, 2022).
bipolar disorder (1 paper, 2010). A disorder of the brain that causes unusual shifts in mood, energy, activity levels and the ability to carry out day-to-day tasks. "Loss of copy number in the gene INPP5B may induce leakage-cleanup of IP3 in the nerve conduction, and then induce patients to lose control of excited emotion, while gain of copy number shows no obviously effect in bipolar disorder." (PMID 20808825, 2010).
cataract (1 paper, 2013). Partial or complete opacity of the crystalline lens of one or both eyes that decreases visual acuity and eventually results in blindness. "The roles of OCRL and INPP5B in the development of cataracts and glaucoma are not understood." (PMID 23805271, 2013).
ciliopathies (1 paper, 2016). "Given the importance of PI signalling in ciliogenesis initiation identified here and the identification of various PI 5-phosphatases (such as INPP5E, INPP5B and OCRL) as causal loci for ciliopathies, we reason that PIPKIγ malfunction may also be correlated with ciliopathies." (PMID 26916822, 2016).
glaucoma (1 paper, 2013). Increased pressure in the eyeball due to obstruction of the outflow of aqueous humor. "This study analyzes the intracellular localization and interactions of OCRL and INPP5B in ocular tissues responsible for cataract and glaucoma development." (PMID 23805271, 2013). "Taken together, OCRL and INPP5B are differentially expressed in the ocular tissues involved in glaucoma and cataract development." (PMID 23805271, 2013).
glioblastoma (1 paper, 2021). The most malignant astrocytic tumor (WHO grade IV). "INPP5B and SYNJ2 are from the same gene family and could potentially control the motility of glioblastoma cells." (PMID 33641617, 2021).
hepatocellular carcinoma (1 paper, 2022). A malignant tumor that arises from hepatocytes. "Furthermore, changes in the expression of INPP5B have also been found in the metabolomic data of hepatocellular carcinoma." (PMID 35568951, 2022).
Infertility (1 paper, 2025). "Phosphatidylinositol phosphatase (INPP5B) deficiency affects spermatogenesis and maturation, leading to infertility." (PMID 40777826, 2025).
male infertility (1 paper, 2020). The inability of the male to effect fertilization of an ovum after a specified period of unprotected intercourse. "The deletion of another member of the INPP family, INPP5B, causes male infertility in mice due to a reduced sperm count, motility, and fertilization defects." (PMID 32413098, 2020).
metastatic tumor (1 paper, 2022). "Furthermore, the metastatic tumor expressed lower levels of INPP5B than the non-metastatic primary tumor or normal lung tissues." (PMID 35568951, 2022).
pancreatic cancer (1 paper, 2024). "KIAA1217, SLC44A1, INPP5B, and SDK1 were reversely correlated with some miRNAs not affecting patient survival, which shows these are potential therapeutic targets for pancreatic cancer." (PMID 38741142, 2024).
prostate adenocarcinoma (1 paper, 2025). "It was determined that 21 proteins (DHX9, EIF5, HPRT1, INPP5B, MCM6, PPP6C, SYF2, etc.)whose expression was increased in PC3‐R cells based on label‐free nLC‐MS/MS analysis were consistent with both TCGA prostate adenocarcinoma N0 and N1 nodal metastasis status and correlation data." (PMID 39799471, 2025).
cancer (4 papers, 2022 to 2024). A tumor composed of atypical neoplastic, often pleomorphic cells that invade other tissues. "INPP5B (Inositol Polyphosphate-5-Phosphatase) is an anti-apoptotic protein with a proliferative role in different cancer types and epimutations were observed in 130 individuals in all 5 tissues." (PMID 38475971, 2024). "Meanwhile, LUAD tissues with lower INPP5B expression exhibited higher cancer stemness properties." (PMID 35568951, 2022).
tumor (3 papers, 2016 to 2022). "After identifying the anti-tumor properties and mechanism of INPP5B, we wanted to explore the underlying cause of the down-expression of INPP5B in LUAD patients." (PMID 35568951, 2022). "Mutations in PIK3CA (25.9%), INPP5B (30.8%), SRC (99%) and TSC2 (46.7%) were observed in Tumor #3, and Tumor #4 harbored an NF1 gene mutation (43.5%)." (PMID 27057633, 2016). "In addition, all neoplasms harbored mutations that directly or indirectly affected either the regulation or activation of the PI3K pathway (PIK3CA, NF1, INPP5B and GSK3B)." (PMID 27057633, 2016). "Interestingly, the differential expression of INPP5B in TMN staging and proliferative subtypes of LUAD, to some extent, reflected that INPP5B might affect tumor proliferation and metastasis." (PMID 35568951, 2022). "In conclusion, INPP5B is a potential tumor suppressor gene that has not yet been experimented, and RASAL2 may have a bidirectional effect on tumors, however, both require further study." (PMID 34430085, 2021). "We also found that INPP5B may be a potential tumor suppressor gene that has never been reported in tumors, and there is a variety of evidence to demonstrate the important role of inositol polyphospho-5 phosphatase family in signal transduction, cell adhesion, and migration." (PMID 34430085, 2021).
kidney disease (1 paper, 2020). "INPP5B impairment has been associated with severe renal phenotypes, such as proximal-tubule endocytosis, and targeting NFE2L2 (NRF2) has been tested as a method of preventing kidney disease progression." (PMID 32386536, 2020).
INPP5B also shares sentences with these, for which no sentence is quoted: lung carcinoma (2 papers); schizophrenia (2); infection (1); Intellectual disability (1); liver fibrosis (1); melanocytic neoplasm (1); microcephaly (1); microtia (1); Pectus carinatum (1); retinitis pigmentosa (1); Type 2 DENT disease (1).